CXCL10 (C-X-C motif chemokine ligand 10)
Diseases named in the same sentence as CXCL10 in open-access papers (continued):
Sharing a sentence is not in itself a finding about the gene and the disease.
cancer (continued). "Additionally, EHMT2 loss increased the expression of chemokines such as CXCL10 and CCL27 in cancer cells, promoting NK cell migration." (PMID 41366520, 2026). "Notably, we found both CD4+ and CD8+ CD103+ T co-localised with CXCL10 macrophages, as was noted in other cancers, albeit at a lower spatial profiling resolution." (PMID 41542042, 2026). "Notably, we observed a strong spatial association between cancer proximal Tfh-like cells (analogous to C06b CD103+ Tfh-like cells) and CXCL10+ macrophages." (PMID 41542042, 2026). "CXCL10, also known as human interferon-inducible protein 10 (IP-10), is an intrinsic cytokine involved in regulating adaptive immune response and plays a vital role in combating infections and malignant tumors." (PMID 40839565, 2025). "Basal level of CXCL10 was minimal in cancer cells cultured alone (green bar)." (PMID 41246302, 2025). "In addition, developing nano ‎formulations ‎that deliver CXCL10 directly to target ‎sites offers a more precise method to ensure ‎ CXCL10 expression ‎specifically in cancer cells, ‎thereby increasing therapeutic benefit and specificity." (PMID 40760734, 2025). "As a result, SFV-infected cancer cells significantly altered cytokine and chemokine profiles, reducing immunosuppressive factors (e.g., IL-10) and increasing inflammatory mediators (e.g., CXCL10 and CCL4)." (PMID 40547518, 2025). "Previous studies have reported that CXCL10 promotes metastasis and progression in cancer cells." (PMID 41156624, 2025). "In summary, we observed that TLR3 is highly expressed in ESCC lines and that its activation strongly induces expression of CXCL10, which is a major mediator of an antitumor immune response that may improve prognosis in cancer patients." (PMID 40029556, 2025). "CXCL10, involved in processes such as regulation of cell growth, differentiation, chemotaxis, and activation of peripheral immune cells, plays crucial roles in cancer‐specific pathways." (PMID 40287845, 2025). "The combination of CXCL10 modulation with immune checkpoint inhibitors (e.g. PD-1/PD-L1 inhibitors), cancer vaccines or CAR T-cell therapies may improve overall therapeutic efficacy through synergistic enhancement of the immune response." (PMID 41376630, 2025). "Incorporating CXCL10 profiling into routine cancer diagnostics could not only help predict response to therapy but also prevent treatment failure due to inappropriate modulation." (PMID 40760734, 2025). "STAT2 depletion in USP5-deficient cancer cells significantly reduced upregulated CXCL9 and CXCL10 mRNA, as well as CD86 and HLA-DR protein of cocultured THP1-MΦ; these reductions were rescued by restoring WT-STAT2 but not the Y690A mutant in USP5-depleted cells." (PMID 41321309, 2025). "Additionally, IFN‐inducible chemokines CCL2, CCL5, and CXCL10 were found to be upregulated at both mRNA and protein levels in multiple cancer cells post‐irradiation." (PMID 40470716, 2025). "Furthermore, both drugs suppressed IFNγ-dependent CXCL10 and PD-L1 expression in-vitro in primary human lung cells and human cancer cells." (PMID 40264756, 2025). "SFV/IFNγ inhibited cancer-associated pathways (angiogenesis, glycolysis and extracellular matrix (ECM) remodelling) and enhanced cytotoxic lymphocyte (CTL) chemoattractants (CXCL9 and CXCL10)." (PMID 40547518, 2025). "Notably, mitophagy has also been found to interact with TLR9 to promote the production of the chemokine CXCL10 by cancer cells, which further promotes T-cell recruitment and thus enhances the efficacy of immunotherapy." (PMID 40002724, 2025). "MTAP-KO cancer cells displayed significantly lower luciferase activity, and deletion mapping localized the responsible regulatory elements to the proximal 1-kb region of the CXCL10 promoter." (PMID 41246302, 2025). "Interestingly, lamin-deficient cancer cells were found to present higher expression levels of many inflammatory chemokines such as CCL2, CCL9, CCL22, CXCL9, and CXCL10." (PMID 40708945, 2025).
cancer (continued). "Therefore, antibodies directed against CXCL10 represent a promising class of biologics that offer dual benefits by modulating chronic inflammation and reprogramming immune responses in cancer and immune-mediated diseases." (PMID 40760734, 2025). "To evaluate the possible extension of the CXCL10- IFN-γ axis to the cancer cells, we first evaluated whether IFN-γ also induced CXCL10 production in various murine and human cancer cell lines." (PMID 39474427, 2024). "Further, cancer cells can upregulate the production of CCR7/8 and CXCR4/5, which interact to the corresponding receptors from the lymph node namely CCL1/21 and CXCL10/12 respectively, resulting in the migration of cancer cells to the lymphatic vessels by chemotaxis." (PMID 38940900, 2024). "To validate our model, we tested the individual PaC cell and the combined effects with cancer-associated fibroblasts (CAFs) on cancer tumorigenicity, the cellular interaction through the CXCR3/CXCL10 axis, and cellular responses reflection of anti-cancer treatments." (PMID 38495500, 2024). "Furthermore, M-MDSCs are increased in patients who have recurrent cancer after liver transplantation in a C-X-C motif chemokine ligand 10 (CXCL-10) dependent manner and drive HCC recurrence." (PMID 38474232, 2024). "Our data suggest a potential use of CXCL9-Fc and/or CXCL10-Fc for cancer immunotherapy." (PMID 39474427, 2024). "Other chemokines, including CXCL4, CCL19, and CXCL10, may aid in recruiting immune cells, increasing their cytotoxicity against cancer cells, and inducing apoptosis of malignant cells." (PMID 38475811, 2024). "In addition, the downregulation of IL-15 and CXCL10 in cancer cells from TLS-low tumors was also observed in an independent single-cell RNA-sequencing dataset." (PMID 37348499, 2023). "In addition to its role as a chemotactic factor, CXCL10 is involved in cancer cell growth, apoptosis, and angiogenesis." (PMID 37048082, 2023). "However, only the functional roles of intratumoral CXCL9 and CXCL10 have been investigated phenotypically, with findings indicating that they contribute to cancer proliferation and migration." (PMID 38104126, 2023). "Additionally, it was also proven that blocking CXCL10 enhanced morphine antinociception in cancer-induced bone pain and, from another chemokine family, CX3CL1 plays an important role in regulating morphine analgesia in naive animals." (PMID 37190544, 2023). "CXCL10 promotes CXCR3 expressing cancer cells transported to bone." (PMID 36750966, 2023). "It has been shown that the level of CXCL10 in the blood is correlated with cancer-related fatigue." (PMID 37760523, 2023). "CXCL10 has also been proposed as a target for cancer therapy." (PMID 37296899, 2023). "Conversely, CXCL10 levels showed to correlate with cancer cell invasiveness in other studies." (PMID 36479091, 2022). "Thus, the dynamic changes of CXCL10 in cancer progression and its relationship with Tregs during this change need to be further studied." (PMID 35083488, 2022). "The results that serum CXCL10 concentrations of the patients with advanced CESC were higher than those with early stages of CESC suggested CXCL10 took apart in the process of CESC progression because tumors with late stages were usually cancers with metastases." (PMID 36207693, 2022). "However, cancer cells were also able to produce CXCL10 to a lesser extent in some patients before commencing therapy with anti-PD-1." (PMID 35626062, 2022). "These include dsDNA that binds to TLR7/8/9 on innate immune cells (such as neutrophils) regulating their activation and anticancer activity and dsRNA that, by binding to TLR3 on other cancer cells, induces the production and release of type I interferon and in turn, CXCL10." (PMID 36139473, 2022). "Besides these direct functions on immune cells, dying cancer cell-derived type I IFN also triggers the synthesis of CXCL10 via an autocrine signaling loop." (PMID 36429101, 2022).
cancer (continued). "Importantly, HLA-I+ cancer cells secreted sustained levels of the chemotactic factors CXCL10, CCL4, CCL5, and IFN-γ cytokine in contrast to the HLA-I– cancer cells." (PMID 35503263, 2022). "Finally, ICD is characterized by the activation of an intrinsic type I interferons (IFNs) pathway which triggers the CXCL10 release by dying cancer cells in an autocrine signaling loop." (PMID 36429101, 2022). "On the one hand, CXCL10 secreted by TA-MSCs bind to its cognate receptors CXCR3 presented in cancer cells, and simultaneously, CXCL16 derived from cancer cell bind to CXCR6 on TA-MSCs surface, eventually potentiating the recruitment of TA-MSCs into tumor areas." (PMID 36324128, 2022). "Thus, ICD inducers are able to induce the CXCL10 secretion by cancer cells, raising CXCL10 as another ICD feature." (PMID 36429101, 2022). "Chemokine 10 (CXCL10) attracts leukocytes to infiltrate the cancer tissue." (PMID 35534879, 2022). "One possible explanation for these results might be that the cancer tissues were the major source of serum CXCL10 in patients with CESC." (PMID 36207693, 2022). "Moreover, in cancer-induced bone pain, inhibition of CXCL10, CXCL11 and CXCL13 enhanced morphine analgesic properties in rats." (PMID 36618360, 2022). "In addition, ECM components produced by CAFs and CAFs-derived cytokines including C-C motif chemokine ligand 5 (CCL5), IL6, and C-X-C motif chemokine ligand 10 (CXCL10) were found to regulate cancer cell metabolism by impacting on different signaling pathways." (PMID 34852849, 2021). "p-value < 0.01 was evidenced in both the cancer types for CXCL10." (PMID 33585826, 2021). "CXCL10 has been reported to be involved in cancer-induced bone pain." (PMID 34659199, 2021). "CXCL10 is a member of the CXC chemokine family that mediates the recruitment of CXCR3+ CD4+ Type-1 helper (Th1), CD8+ effector and NK cells to inflammatory sites, and has been implicated in the progression of several cancer types." (PMID 34200333, 2021). "Moreover, the expression of CXCL10 is considered an independent prognostic factor for cancer recurrence in CRC, while the co-expression of both CXCR3 and CXCL10 in CRC is linked to poorer prognosis and metastatic recurrence." (PMID 34071492, 2021). "Aside from our study that used peripheral administration of CXCL10-Ig for cancer immunotherapy." (PMID 34944943, 2021). "Besides the different cancer stages, we also found an elevated level of CXCL10 expression based on different age groups of LUAD and LUSC patients." (PMID 33585826, 2021). "However, the top CXCL10-related LR pair, which we identified as a positive biomarker for all cancer types, is CXCL10 → SDC4." (PMID 34430923, 2021). "CXCL10 has been recently shown to promote a stem‐cell like phenotype in cancer cells." (PMID 33476079, 2021). "Notably, CXCL10 is an important lymphocyte chemoattractant to mediate the cross-talk between cancer and immune cells." (PMID 34386037, 2021). "Stabilized CXCL9 and CXCL10 are likely to be good candidates for immunotherapy of cancer diseases." (PMID 34944943, 2021). "By combining RNAscope with IHC we could confirm a M1 Mφ identity of a fraction of CXCL10+ cells, in addition to CXCL10+ cancer cells." (PMID 34220848, 2021). "GSEA pathway enrichment analysis revealed downregulation of CXCL10 in multiple cancer pathways." (PMID 33345267, 2021). "C-X-C motif chemokine ligand 10, also named IP-10, is a potent chemokine for activated T lymphocytes and regulates cell proliferation, apoptosis, and angiogenesis in infectious and inflammatory diseases and cancer." (PMID 34790658, 2021). "These latter act in an autocrine and paracrine manner to stimulate the secretion of the chemokine C-X-C motif chemokine ligand 10 (CXCL10) by cancer cells and thus favor the recruitment of activated T cells expressing its receptor, C-X-C motif chemokine receptor 3 (CXCR3)." (PMID 33281620, 2020). "Collectively this applies for an anti-cancer property of CXCL10." (PMID 32547545, 2020).
cancer (continued). "Furthermore, it is now widely established that cancer cells with DDR deficiency exhibit constitutive activation of cellular IFN responses and secretion of TIL recruiting chemokines, CCL5 and CXCL10." (PMID 31174611, 2019). "Additionally, however, we noted a specific set of genes encoding chemokines and cytokines, namely CCL4, CCL8, CXCL10, CXCL11, IFI44L, IDO1, and IFNG that were upregulated in 9p CNG cancers." (PMID 29212506, 2017). "High-expressed gene CXCL10 was chosen for further cell experiment, and the results indicated that CXCL10 can promote the proliferation, migration and invasion of normal cells and inhibited the cancer cells after si-RNA transfection." (PMID 28176846, 2017). "Moreover, wound healing experiment showed normal cells speed up with low expressed CXCL10, while cancer cells demonstrated an obvious decline." (PMID 28176846, 2017). "Finally, animal models of human cancers suggest that type I IFN-induced expression of CXCL10 by cancer cells plays a major role in the success of anti-cancer therapies, implicating T cell-selective chemoattraction as a relevant component of this response." (PMID 29064427, 2017). "However, the molecular mechanisms by which CXCL10 regulated cancer cell proliferation and invasion remained unclear." (PMID 28176846, 2017). "However, blocking CXCL10 spinal function enhanced the morphine antinociceptive properties in rats with cancer-induced bone pain." (PMID 28337574, 2017). "Previous studies found that CXCL10 was a novel candidate oncogene which may be a therapeutic target for several types of human cancer." (PMID 28176846, 2017). "The CXCL10/CXCR3 axis has been regarded as an important regulator in cancer cell invasion." (PMID 26506595, 2016). "CCL21 and CXCL10 transcript levels were comparable between the cancer and unaffected tissues." (PMID 27517754, 2016). "Indeed, recent research found that Cxcl10 and its receptor Cxcr3 were involved in inflammatory pain and cancer pain." (PMID 26184882, 2015). "Because IFN-γ affects the cancer immunoediting process, we examined whether the expression of CXCL10 is regulated by HO-1 in IFN-γ-stimulated CRC cells." (PMID 26087182, 2015). "Using CXCL10 as a representative of CTL-attracting chemokines, involved in attraction of CXCR3+ CTL implicated with good prognosis for cancer patients, we tested whether BCG treatment can enhance intra-tumoral production CXCL10." (PMID 25806105, 2015). "Of note, we observed that the protein levels of CXCL10 in cancer and normal tissues were significantly positively correlated, which may reflect individual differences in the basal expression of CXCL10." (PMID 24748971, 2014). "A likely explanation for this may be that the leakage of CXCL10 from cancer tissue is controlled by increased MMP activity due to the higher disease stage." (PMID 24748971, 2014). "The presence of transient PD-L1+/CXCL9+/CXCL10+ myeloid clusters at sites that later develop tumors suggests that immune organization itself may serve as an early biomarker—and potentially a therapeutic target—for cancer interception." (PMID 41279770, 2025). "Therefore, drugs that upregulated IFN-γ dependent CXCL10 and PD-L1 expression in our screening may be considered as good candidates for cancer immunotherapy." (PMID 40264756, 2025). "Moreover, corresponding to the significant interaction of chemokine module 1 with receptor module 4 (expressed on, e.g., T cells) in the analyzed PDAC patient data, we observed release of module 1 chemokines (CCL5 and CXCL10) by irradiated cancer cells with subsequent recruitment of T cell subsets." (PMID 40811032, 2025). "Similarly, while the binding of CXCL10 to the chemokine receptor CXCR3-B inhibits cancer cell proliferation, it can also activate another splice variant of CXCR3, CXCR3-A, which can induce chemotaxis and cancer cell proliferation." (PMID 38543085, 2024).
cancer (continued). "Interestingly, apoptotic cancer cells release epigenetically regulated cytokines including CXCL10 and CCL2, enhancing nucleic acid-elicited phagocytosis of dying cancer cells by neutrophils, providing alternative approaches for neutrophil-based anticancer therapy." (PMID 37928272, 2023). "TNF-α expression was observed to upregulate expression of several cancer-associated genes in the epithelial cells which include extracellular matrix (ECM) remodeling genes such as MMP9, PLAU, FN1 and ICAM1, chemokines such as CCL2, CXCL2, CXCL3 and CXCL10 and regulatory genes such as UBD and PTGS2." (PMID 34946170, 2021). "Finally, we discuss the possibility that CXCL9 and CXCL10 may differ in their biological function via biased signaling and its possible relevance to cancer immunotherapy." (PMID 32547545, 2020). "In addition, it was reported that CXCL10 is involved in the recruitment of CXCR3-expressing cancer cells to the bone marrow leading to bone metastasis formation, induction of osteoclast differentiation and osteolysis, while treatment with anti-CXCL10 antibody decreased metastasis formation in vivo." (PMID 31572390, 2019). "Besides, CXCL10 can promote cancer cell apoptosis by interfering oncogene expression." (PMID 28176846, 2017). "CXCL10 may be expressed and secreted by various types of cells, such as monocytes/macrophages, endothelial cells, fibroblasts and dendritic cells, thereby masking the local changes in CXCL10 levels attributed to cancer cells." (PMID 24748971, 2014). "Mph), which promotes CD4+ T cell accumulation via CXCL10/CXCR3 for HLA-DR+ Schwann cells and assists them in shaping the cancer-neuron-immune niche and facilitating HNSCC progression." (PMID 42295734, 2026). "FGFR4-overexpressing cancer cells induced CAF differentiation/activation and exhibited higher concentrations of CXCL10 than control cells." (PMID 40447617, 2025). "Intriguingly, apart from the T cell chemokines CXCL9 and CXCL10, we observed upregulation of surface MHC-I expression upon UBA1 inhibition or depletion in various cancer models." (PMID 39540840, 2025). "TNF-α induces the expression and secretion of CXCL1, CXCL10 and several CCL chemokines in immune cells, endothelial cells and cancer cells." (PMID 40833805, 2025). "Our results after MAVS knockdown suggest that either RIG-I or MDA5 is involved in the CXCL10 secretion by cancer cells and that the TLR3 pathway contributes at least as much to CXCL10 secretion as the MAVS pathway." (PMID 40029556, 2025). "CXCL9, CXCL10, and CXCL11 are selective ligands for the C‐X‐C motif chemokine receptor 3 (CXCR3) and are secreted by cancer cells." (PMID 40105652, 2025). "In a phase I trial of intravenous Helixor® M in advanced cancer patients, treatment resulted in increased levels of CXCL9 and CXCL10, chemokines that mediate the recruitment of cytotoxic T and NK cells to solid tumors." (PMID 40864825, 2025). "Promising strategies include oncolytic viruses engineered to express CXCL10, which have shown efficacy in reprogramming the TME in other cancers by providing a sustained, high-concentration local chemokine source." (PMID 41516196, 2025). "On the other hand, CXCL10 and CXCL11 have been described to enhance cancer development, possibly by promoting angiogenesis and metastasis." (PMID 40895532, 2025). "Baseline expression levels of CXCL9, CXCL10, and CXCL11 were relatively low and comparable between MTAP-WT and MTAP-KO CL1–0 and 786–0 cancer cells, as well as between CL1–5 Mock and MTAP-expressing cells." (PMID 41246302, 2025). "Further analysis using the TCGA pan-cancer dataset consolidated the positive correlation between MTAP and CXCL10 expression." (PMID 41246302, 2025). "KTC1101 acts directly on immune cells to modulate T cell populations but also stimulates cancer cells to produce inflammatory cytokines, such as chemokine ligand 5 (CCL5) and C-X-C motif chemokine ligand 10 (CXCL10), which promotes CD8+ T cell chemotaxis." (PMID 40362630, 2025).